AK4 (adenylate kinase 4)
Diseases named in the same sentence as AK4 in open-access papers (continued):
Sharing a sentence is not in itself a finding about the gene and the disease.
tumor (21 papers, 2016 to 2025). "Several studies have investigated the mechanisms underlying AK4 expression and tumor metastasis." (PMID 40593461, 2025). "Additionally, the use of AK4 LUAD tumor gene signatures is associated with the oncogenic protein RAD52 motif Containing 1 (RDM1) at the LUAD tumor stage 2–3 and 3–4 interfaces." (PMID 34940617, 2021). "Thus, our AK4-driven signature identifies known pro-oncogenic factors, lending credibility to our signature, and also suggests previously unidentified tumor stage associations with these known pro-oncogenic factors." (PMID 34940617, 2021). "On the basis of previous research, two genes, UACA and AK4 that may be associated with the anti-tumor mechanism of MA, were screened and discussed." (PMID 34637398, 2021). "AK4 is overexpressed in OC and the expression level is significantly correlated with tumor size and FIGO stage." (PMID 35964092, 2022). "In this study, we use LUAD patient primary tumor transcriptome data across stages 1–4 to analyze AK co-expression signatures that reveal potential AK4-driven hallmarks of tumor development and metastasis." (PMID 34940617, 2021). "Using our prior knowledge of LUAD patient tumor stage, we additionally incorporated this network—comprised of individual AK4 gene signatures—to predict genes that contribute to tumor progression or regression via sPLS-DA." (PMID 34940617, 2021). "Co-expression analysis of all AK isoforms reveals AK4 transcript levels to increasingly correlate with a LUAD-specific hypoxia signature throughout early LUAD tumor development, leading up to metastasis." (PMID 34940617, 2021). "It was also observed that AK4 has a unique expression pattern that split tumor samples into two major clusters." (PMID 34940617, 2021). "Here, we opted to employ sPLS-DA using LUAD tumor stage-specific AK4 gene signatures to extract key genes capable of discriminating tumor progression or regression." (PMID 34940617, 2021). "Collectively, these results expand the scope of influence that AK4 exerts on pathological LUAD tumor dynamics." (PMID 34940617, 2021). "We found that AK4 was involved in hypoxia tolerance, resistance to anti-tumor drug, and the regulation of mitochondrial activity." (PMID 26980435, 2016). "Subcutaneous grafting AK4 knockdown cells into nude mice revealed that the grafted cells exhibited both slower proliferation and reduced the tumor sizes in response to CDDP." (PMID 26980435, 2016). "To examine the role of AK4 on cell growth in vivo, we implanted AK4 knockdown HeLa cells into nude mice and analyzed the tumor size." (PMID 26980435, 2016). "Tumor volume composed of HeLa cells transfected with AK4 shRNA showed smaller (53.2 %) compared with those transfected with control shRNA." (PMID 26980435, 2016). "AK4 links to a GBM-specific module enriched for cellular tumor genes." (PMID 39516198, 2024). "However, the expression of AK3/4 among major tumor stages demonstrated that only AK4 possessed a statistical difference." (PMID 35220277, 2022). "Besides, AK4 favors tumor development and metastasis in an ATF3-dependent manner, which interestingly plays contradictory roles of either inducing apoptosis or promoting proliferation in different types of OC." (PMID 35964092, 2022). "Mass spectrometry-based proteomics revealed that DEN-induced tumor mitochondria had increased expression of adenylate kinase isoform 4 (AK4), which may account for this response to Ap5A." (PMID 35756609, 2022). "AK4 was also shown to interact with HIF-1 signaling under hypoxic conditions in m1 macrophages which further supports the interaction to be a global response in a tumor microenvironment." (PMID 34940617, 2021). "In doing so, we reveal a dynamic association between AK transcript expression and hypoxia in the context of LUAD tumor development, specifically highlighting an increasingly positive correlation between AK4 levels and hypoxia as LUAD tumor development continues." (PMID 34940617, 2021).
tumor (continued). "This moved us to assess whether there were any significant changes in AK4 expression, along with the other AKs, within tumor stages." (PMID 34940617, 2021). "Therefore, we sought to characterize AK4-related co-expression networks across LUAD tumor stages 1–4." (PMID 34940617, 2021). "Additionally, at all LUAD tumor stage-to-stage interfaces, there was an overwhelming amount of consensus between genes in the AK4 gene signatures that—via sPLS-DA—predicted LUAD tumor advancement and the survival analysis." (PMID 34940617, 2021). "AK4 was involved in hypoxia tolerance and resistance to anti-tumor drugs." (PMID 32549791, 2020). "Furthermore, we detected the level of AK4 and Ki67 (an indicator of tumor cell proliferation) by the immune-histological analysis in the tumor sections." (PMID 29866054, 2018). "The intratumoral injection of an miR-199a-3p agomiR into G-292 indeed led to a decrease of the AK4 level in the tumor sections, which further confirmed that miR-199a-3p has a negative effect on both the growth and drug resistance of OS cell-derived tumor xenografts in nude mice." (PMID 29866054, 2018). "Furthermore, we performed in vitro and in vivo experiments in cultured cells and tumor xenografts to address the roles of miR-199a-3p and AK4 in OS drug resistance." (PMID 29866054, 2018). "Tumor sizes formed by AK4 knockdown cells are significantly smaller than those by control cells." (PMID 26980435, 2016). "Additionally, AK4 expression is correlated with tumor invasion." (PMID 40593461, 2025). "Collectively, these results characterize regulatory gene networks associated with the expression of all nine human AKs that may contribute to underlying metabolic perturbations within LUAD and reveal potential mechanistic insight into the complementary role of AK4 in LUAD tumor development." (PMID 34940617, 2021). "Moreover, the use of sparse partial least squares discriminant analysis (sPLS-DA) against LUAD tumor stage-to-stage interfaces within the AK4 co-expression network identified candidate genes that may contribute to LUAD tumor growth or regression." (PMID 34940617, 2021). "Enrichment analysis of LUAD tumor AK4 gene signatures predicts signatures involved in pyrimidine, and by extension, nucleotide metabolism across all LUAD tumor stages." (PMID 34940617, 2021). "Three of the nine isoforms demonstrated significant changes between tumor stages (ANOVA, p* <0.05), with AK4/7 expression appearing to increase and AK9 expression to decrease with tumor stage." (PMID 34940617, 2021). "Using this approach, we constructed AK4 gene signatures across LUAD stage 1–4 differentially expressed genes, effectively creating a LUAD tumor AK4 co-expression network." (PMID 34940617, 2021). "All of CRABP2, DHCR24, and AK4 showed cytoplasmic staining of tumor cells, but no staining was evident in the stroma." (PMID 37004157, 2023). "Although it has been reported that knockdown of AK4 can significantly inhibit the migration and invasion of CRC cells under hypoxia, the specific molecular mechanism and its effect on tumour cell proliferation are still unknown." (PMID 35789070, 2022). "Using these AK4 co-expression networks, we next sought to identify potential drivers of LUAD tumor progression using a staggered classification approach to predict genes that contribute to tumor growth or regression at tumor stage-to-stage interfaces." (PMID 34940617, 2021). "Nonetheless, this report expands on the associations between perturbed AK isoform expression and LUAD hypoxic status, and collectively reveals potential mechanistic insight into how AK4 serves as a negative prognostic marker in LUAD tumor development." (PMID 34940617, 2021). "Interestingly, at the stage 1–2 AK4 gene signature interface, the pyrimidine salvage protein thymidine kinase 1 (TK1) was predicted to be amongst the most influential for LUAD tumor progression from stage 1 to stage 2." (PMID 34940617, 2021).
tumor (continued). "The results showed that CLDN9, AK4, PC, GPC1, and SRD5A3 were upregulated in EC tissues compared to in normal endometrium tissues, whereas B4GALT1, GMPPB, B4GALT4, and CHST6 were downregulated in tumor tissues." (PMID 31807118, 2019). "Tumor and normal tissue microarray data (NPC, GSE12452, GSE53819; head and neck tumor, the Cancer Genome Atlas) revealed that AK4 was the only gene that was upregulated in both NPC and head and neck tumor samples compared to normal samples among the gene signatures (AK4, CPAMD8, DDAH1, and CRTR1)." (PMID 40593461, 2025). "In normal lung tissue adjacent to the tumor, CRABP2, DHCR24, and AK4 were observed in bronchial epithelial cells, but not in alveolar pneumocytes." (PMID 37004157, 2023). "Interestingly, of the few genes that, via sPLS-DA, were predicted to contribute to tumor regression at certain stage-to-stage interfaces—including DAPK2, PLAC9, ABCB9, MELTF, CTHRC1, and OCIAD2, testing for LUAD patient survivability via AK4 combination resulted in a negative prognosis." (PMID 34940617, 2021).
infection (2 papers, 2021 to 2026). The state of being infected such as from the introduction of a foreign agent such as serum, vaccine, antigenic substance or organism. "Our results suggest that induction of Ak4 after infection produces more dADP, whose conversion to dATP in mitochondria supports mtDNA synthesis and the subsequent increase of mtROS production." (PMID 41817449, 2026). "Interestingly, adenylate kinase 4 (Ak4) expression was upregulated in macrophages after infection." (PMID 41817449, 2026).
adenocarcinoma (1 paper, 2023). A common cancer characterized by the presence of malignant glandular cells. "Using IHC, the protein expressions of CRABP2, DHCR24, and AK4 were examined using 44 adenocarcinomas including AIS (n = 7), MIA (n = 21), and SIA (n = 16)." (PMID 37004157, 2023).
bacterial infection (1 paper, 2026). "Ak4 KO mice as well as macrophage-specific Ak4 KO mice became highly susceptible to bacterial infections." (PMID 41817449, 2026). "Ak4 is critical for the increase of mtDNA synthesis and mitochondrial mass in macrophages after bacterial infection." (PMID 41817449, 2026).
head and neck tumor (1 paper, 2025). "In addition, microarray analysis (GSE13597, GSE53819, and TCGA) revealed that AK4 expression was positively correlated to IL-1β expression in NPC and head and neck tumor samples." (PMID 40593461, 2025).
AK4 also shares sentences with these, for which no sentence is quoted: amyotrophic lateral sclerosis (1 paper); bipolar disorder (1); colorectal adenocarcinoma (1); COVID-19 (1); Hypertension (1); myelodysplastic syndrome (1); nasopharyngeal carcinoma (1); neuroblastoma (1); neurodegenerative disease (1); oral squamous cell carcinoma (1); pancreatic ductal adenocarcinoma (1); severe combined immunodeficiency (1).